TREM2 (triggering receptor expressed on myeloid cells 2)
Diseases named in the same sentence as TREM2 in open-access papers (continued):
Sharing a sentence is not in itself a finding about the gene and the disease.
amyloid (continued). "TREM2 was correlated with Iba1, TMEM119, and CD68, consistent with TREM2 upregulation in specific phenotypes of disease or amyloid-associated microglia." (PMID 33178186, 2020). "The current findings are also broadly consistent with a previous brain autopsy study reporting that individuals carrying TREM2 mutations exhibit lower amyloid plaque‐associated microglia activation, less microglial clustering, and higher neuritic plaque score." (PMID 32790063, 2020). "TREM1, which shares homology with TREM2, has also been linked to AD amyloid pathology and cognitive decline." (PMID 30746447, 2019). "Recent studies have revealed that myeloid cell accumulation around amyloid plaques was reduced in TREM2 hemizygous and DAP12-deficient AD mouse models." (PMID 29655369, 2018). "In AD, increased expression of TREM2 has been confirmed in patients and in mouse models of amyloid and tau pathology and seems to be associated with the recruitment of microglia to amyloid plaques." (PMID 30572908, 2018). "It was consistently reported that the number of microglia around amyloid plaques was reduced in Trem2-deficient amyloid mouse models, leading to an increase in less compact plaques." (PMID 29587871, 2018). "Using this model, we demonstrate that the Trem2 R47H variant dramatically reduces TREM2 expression, compromising myeloid cell responses to AD-like amyloid pathology." (PMID 29859094, 2018). "Rare, coding TREM2 variants that increase risk of AD appear to have loss of function effects and are associated with reduced amyloid plaque-associated microgliosis." (PMID 30326945, 2018). "There was also a significant reduction in neurons in layer V of the cortex in TREM2 deficient amyloid models of AD and a substantial rescue of neuronal loss when TREM2 was overexpressed in amyloid and tau AD mouse models." (PMID 28768545, 2017). "Studies examining loss of TREM2 function in amyloid mouse models initially appeared to support contradictory conclusions." (PMID 28768545, 2017). "Another upregulated gene is TREM2, which is also upregulated in amyloid-plaque-associated MG and contains variant alleles that increase AD risk." (PMID 28076797, 2017). "This upregulation of TREM2 expression occurs shortly after the onset of pathology and largely seems to correlate with amyloid burden and the association of myeloid cells with amyloid plaques." (PMID 28768545, 2017). "Albeit compensatory increases of Fc receptor‐mediated phagocytosis, TREM2‐deficient phagocytic cells, showed significantly reduced uptake of antibody‐bound Aβ and as a consequence reduced clearance of amyloid plaques." (PMID 27402340, 2016). "Although the details of how TREM2 modulates risk for AD remain to be clarified, it appears that TREM2 helps to mediate a protective inflammatory response to amyloid pathology." (PMID 26976613, 2016). "In addition, the TREM2 R47H variant was found to impair soluble TREM2 cell-surface interactions, with a decreased TREM2 shedding noted on neurons and around amyloid plaques in the TREM2 R47H KI x 5xFAD mouse model." (PMID 38462606, 2024). "Importantly, our study demonstrates that two distinct subsets of Trem2+ tissue-resident and monocyte-derived macrophages are highly associated with vascular amyloid deposits following Aβ immunotherapy." (PMID 39434125, 2024). "Furthermore, Aβ’s interaction with APOE’s lipid-binding region activates TREM2, contributing to the amyloid plaque-associated TREM2 activation." (PMID 38912524, 2024). "Trem2R47H NSS mice were treated with the demyelinating agent cuprizone, or crossed with the 5xFAD mouse model of amyloidosis, to explore the impact of the TREM2 R47H variant on inflammatory responses to demyelination, plaque development, and the brain’s response to plaques." (PMID 36803190, 2023). "The association between TREM2 and tau pathology was investigated by studies in which TREM2 knock-out dramatically enhanced Aβ-induced tau seeding and spreading around plaques in the amyloid mouse model." (PMID 35741054, 2022).
amyloid (continued). "Several reports AD suggest that TREM2 deficiency results in decreased microglial activation and a subsequent reduction of plaque-associated microglia, which augments local Aβ toxicity and amyloid-induced neuritic dystrophy." (PMID 34289882, 2021). "Finally, constitutive deletion of Rev‐erbα in the 5XFAD model of AD decreased amyloid plaque number and size and prevented plaque‐associated increases in disease‐associated microglia markers including TREM2, CD45, and Clec7a." (PMID 31800167, 2020). "In APP‐PS1 mice, which show widespread amyloid plaques in the brain by 3–4 months of age, TREM2 knockdown was associated with higher amyloid plaque burden at 8 months and 12 months, i.e., when amyloid plaque deposition is already quite expanded but still increasing." (PMID 32790063, 2020). "Human AD patients carrying the TREM2 risk variants have more dystrophic microglia, weaker interaction of microglia with amyloid plaques, increased dystrophic neurites, and larger areas of insoluble phosphorylated tau than age- and disease stage-matched AD patients without an AD risk variant." (PMID 33198789, 2020). "Thus, aggravated neuritic dystrophy is a more consistent outcome of Trem2 deficiency than amyloid plaque load, suggesting that the microglial packing of Aβ into dense plaque is an important neuroprotective activity." (PMID 31980586, 2020). "Interestingly, TREM2 plays distinct functional roles at different stages: in a mouse model of AD, TREM2 deficiency ameliorates amyloid pathology in the early disease stage, but exacerbates the pathology as the disease progresses." (PMID 30498474, 2018). "They reported that only the common variant of TREM2 was able to restore microgliosis and microglial activation induced by amyloid pathology in this model, while mice expressing the R47H variant displayed impaired microglial activation and recruitment to plaques." (PMID 30572908, 2018). "Indeed, TREM2 deficiency prevents the transition of microglia to the MGnD phenotype, which prevents the beneficial effects of microglia on amyloid pathology." (PMID 30572908, 2018). "TREM2 or DAP12 deficiency may lead to excessive proinflammatory microglial activation which causes neurodegeneration with amyloid plaque deposition." (PMID 29361745, 2018). "On the one hand, reduction in TREM2 ameliorated several aspects of AD pathology, including inflammation, astrocytosis, and amyloid plaque burden, while on the other hand, Trem2 deficiency leads to exacerbated disease pathology including increased amyloid plaque burden." (PMID 27402340, 2016). "Notably, TREM2 messenger RNA (mRNA) was upregulated in amyloid plaque-associated versus plaque-free brain tissue of aged APP23 mice, a transgenic AD mouse model." (PMID 27051467, 2016). "These genes, Thy1, Gfap, Tyrobp, Ctsd, Cst7, C1qb, Lyz2, Ctss, Trem2, Mpeg1, Hexb, Cd68, C1qb, C1qa, Ctsz, Grn, Laptm5, B2m, C1qc, Hexa, and Serpina3n, were increased in the 7-month-old 5XFAD model in the cortex and associated with amyloid plaque image patterns." (PMID 38036733, 2023). "The phagocytic function of microglial TREM2 in the early middle pathological stage (2–6 months old mice) exacerbated AD pathology by inducing synaptic loss, while its expression in advanced stages (6–10 months) prevented amyloidosis by limiting amyloid deposition." (PMID 35805174, 2022). "It was also reported that TREM2 slowed AD progression and reduce tau-driven neurodegeneration by restricting the degree to which β-amyloid facilitates the spreading of pathogenic tau, which suggests an interplay among TREM2, tau pathology, and amyloid pathology." (PMID 35717259, 2022). "However, 5xFAD mice carrying the TREM2 H157Y exhibited reduced amyloid pathology, suggesting TREM2 H157Y might impact AD risk through an amyloid-independent pathway, such as its effects on tauopathy." (PMID 36564824, 2022).
amyloid (continued). "Thus, while previous reports have already noted that air pollution can affect plaque load, the discovery that DE impairs TREM2 expression suggests that future mechanistic studies should focus on the effect of urban air pollution on amyloid plaque-associated microglia." (PMID 33222683, 2020). "Triggering receptor expressed on myeloid cells 2 (TREM2) is produced in the CNS in microglial cells and the loss of the anti-inflammatory properties of this receptor is associated with increased tau pathology, and in older mice, increased amyloid plaque in preclinical models of AD." (PMID 33207605, 2020). "However, TREM2‐deficient N9 microglial cell lines, macrophages as well as primary microglia showed significantly reduced uptake of antibody‐bound Aβ and as a consequence reduced clearance of amyloid plaques." (PMID 27402340, 2016). "By integrating genetic, molecular, and clinical evidence, this review establishes TREM2 as a keystone regulator linking amyloidosis, tauopathy, and neuroinflammation, highlighting its promise as a target for disease-modifying therapies." (PMID 41789102, 2026). "In summary, the evidence strongly supports a protective role for TREM2 in amyloid-induced tauopathy, a model more closely resembling AD pathology." (PMID 40247363, 2025). "Generated through the cleavage of the TREM2’s ectodomain by metalloproteases and/or alternative TREM2 splicing, sTREM2 has been shown to reduce amyloidosis, tau hyperphosphorylation, and cognitive deficits in rodent models." (PMID 40165251, 2025). "Overall, TREM2 is widely regarded as protective in amyloid pathology by promoting microglial clustering, phagocytosis, and plaque compaction while reducing neurotoxicity." (PMID 40247363, 2025). "For example, TREM2 has also been shown to contribute to microglial senescence and the accompanying inflammation and cognitive decline in 5xFAD mouse model of amyloidosis." (PMID 40165251, 2025). "Of note, a significant increase of these two Trem2 transcripts was also reported in a recent study using qPCR in two TG amyloid models of AD22, suggesting that these transcripts are upregulated in response to both tau and amyloid pathology." (PMID 39095344, 2024). "The interactions between glial cells and amyloid plaques involve a membrane protein Triggering Receptor Expressed on Myeloid Cells 2 (TREM2)." (PMID 37815901, 2024). "Deletions of TREM2 and ApoE lead to impaired microglial cell response to amyloid plaques; and ApoE4 impairs microglial response in the presence of amyloid." (PMID 39695808, 2024). "In particular, the up-regulation of TREM2 expression, achieved through the overexpression of human TREM2, has demonstrated efficacy in reducing amyloid plaque deposition." (PMID 39596378, 2024). "Studies in mice and previous data from our lab in xenotransplantation models have shown that both the deficiency of TREM2 and APOE can alter the transcriptional response of microglia to amyloid pathology." (PMID 38654375, 2024). "Taken together, these assessments suggest that Trem2 H157Y reduced amyloid burden and Aβ related neurite dystrophy in homozygous mice at the late stage of amyloid development." (PMID 36721205, 2023). "What looks to be an undisputed feature of TREM2 is its role in microglia barrier around the amyloid plaques and in amyloid compaction." (PMID 37274212, 2023). "Transcriptomic profiling revealed that Trem2 H157Y downregulates neuroinflammation-related genes and an immune module correlated with the amyloid pathology." (PMID 36721205, 2023). "A mouse TREM2-specific antibody, 4D9, was previously shown to enhance protective microglial functions and reduce amyloid pathology in an AD mouse model." (PMID 36635496, 2023). "Collectively, these results help to clarify prior data obtained from amyloidosis models crossed with Trem2R47H mice with unintended hypomorph phenotypes, and add to our understanding of how microglia and TREM2 contribute to the pathogenesis of AD." (PMID 36803190, 2023).
amyloid (continued). "Taken together, amyloid pathological analysis in founder 2-linage mice showed consistent results with those from founder 1-linage mice that Trem2 H157Y reduces amyloid burden, dystrophic neurites, and gliosis at 8.5 months of age." (PMID 36721205, 2023). "In the presence of amyloid pathology, Trem2 H157Y accelerates amyloid-β (Aβ) clearance and reduces amyloid burden, dystrophic neurites, and gliosis in two independent founder lines." (PMID 36721205, 2023). "We also demonstrate that ATV:TREM2 increased microglial activity and glucose metabolism in an amyloid mouse model via TSPO-PET and FDG-PET imaging, respectively." (PMID 36635496, 2023). "TREM2 was shown to be required for amyloid plaque compaction in AD mouse models, myelin debris clearance in demyelinating models and neuronal health." (PMID 36635496, 2023). "The effects of Trem2 deficiency on amyloid pathology have been studied in APP transgenic mice with different results based on the mouse model used and the stage of amyloid pathology." (PMID 37274212, 2023). "In the presence of amyloid pathology, Trem2 H157Y accelerated Aβ clearance, and reduced amyloid burden, toxic Aβ oligomer, dystrophic neurites, and gliosis at the late stage of amyloid pathology." (PMID 36721205, 2023). "In vivo studies of the amyloid mouse model reveal the crucial function of TREM2 in the clustering microglia around plaques, plaque compaction, and microglial proliferation." (PMID 35741054, 2022). "AL002a, a variant of AL002 that targets the TREM2 signaling pathway, increased CD11b-positive microglia in the cortex and hippocampus of APP/PS1 mice, enhanced microglial clustering at amyloid plaques, and reduced amyloid deposition in 5×FAD mice." (PMID 35741054, 2022). "Under the relevant conditions of AD, TREM2 interacted with lipoproteins, anionic lipids, and Aβ, contributing to the microglial promotion of amyloid plaque deposition and phagocytosis of cellular tissue debris." (PMID 35966781, 2022). "Higher levels of Trem2 transcripts were detected in methoxy-X04 positive amyloid plaques by in situ hybridization in AppSAA homozygous mice at 8 months of age, consistent with an enrichment of responsive microglia clustering around amyloid plaques." (PMID 35690868, 2022). "Altogether, these results indicate reduced reactivity of TREM2-R47H xMGs to amyloid plaques in chimeric 5X-hCSF1 mice." (PMID 34301296, 2021). "One recent study demonstrates that, in a mouse model of amyloidosis, TREM2 expressed by microglia is able to limit amyloid-induced AD tau seeding and spreading as one potential mechanism tying together amyloid to tau." (PMID 34289882, 2021). "Consistently, TREM2 deficiency in 5 × FAD mice, a genetic AD mouse model, leads to increased amyloid plaques and an increased number of dystrophic neurites, whereas increasing TREM2 levels can reduce plaque area and cognitive impairment in AD mice." (PMID 32677986, 2020). "Considering that APP/E4 mice show earlier onset of amyloid pathology, the TREM2 effect on plaque growth in mice expressing this isoform is observed in mice younger than their APOE3 counterparts." (PMID 32703241, 2020). "Our data support a critical role for Trem2 in microglial phagocytosis with increased microglial clustering at amyloid plaques and reductions in amyloid deposition using a Trem2-activating approach." (PMID 32795308, 2020). "Microglial ability to seal off amyloid plaques from the surrounding neuropil is dependent on TREM2, as knockout mice had significantly reduced plaque area covered by microglia, while displaying increased plaque-associated neuronal dystrophy." (PMID 33408613, 2020). "We studied the effects of Trem2 deletion in the PS2APP mouse AD model, in which overproduction of Aβ peptide leads to amyloid plaque formation and associated neuritic dystrophy." (PMID 31980586, 2020).
amyloid (continued). "Overall, our results are reminiscent of a recent study of APPPS1 mice, which showed that Trem2 deletion produced increased seeding of amyloid plaques at early ages but slower rates of amyloid plaque accumulation at later ages." (PMID 31980586, 2020). "Animal studies have shown that brain levels of soluble TREM2 increase during aging in parallel with amyloidosis and microglia activation." (PMID 33584248, 2020). "Trem2 deletion in amyloidosis models has also been reported to either increase or decrease phosphorylation of the endogenous tau protein." (PMID 31980586, 2020). "This implicates TREM2 in the maintenance of the microglial response to amyloid pathology, further connecting APOE, TREM2, microglia function, and amyloid pathology." (PMID 32703241, 2020). "Of note, a recent report showed that the ectodomain form of TREM2, soluble TREM2, is protective in an amyloid mouse model by enhancing microglial metabolism of Aβ and triggering microglia to an active state." (PMID 32005122, 2020). "One potential explanation is that TREM2 signalling is a beneficial response that supports microglia activation and migration towards amyloid plaques, helping to prevent amyloid spread and damage." (PMID 30740661, 2019). "The lack of function of TREM2, DAP12, or both in AD patients leads to failing amyloid engulfment, determining a similar amyloid-associated AD-type dementia as that observed in NHD." (PMID 29361745, 2018). "Recently, TREM2-APOE pathway was identified as a major regulator of microglia activation in response to amyloid pathology." (PMID 30558641, 2018). "Consistent with this, elevated TREM2 gene dosage reduced amyloid pathology and improved memory in a mouse model of AD." (PMID 30326945, 2018). "TREM2 is strongly expressed in AD brain tissue, notably close to amyloid plaques, and can mediate amyloid plaque phagocytosis." (PMID 29361745, 2018). "In middle-aged APPswe/PS1ΔE9 mice (7–8 months old), the ability of microglia to remove amyloid plaques increased after TREM2 overexpression, and the density of amyloid plaques in the brain decreased." (PMID 29655369, 2018). "One study reports a reduction in TREM2 RNA levels before the onset of pathology in Tg2576 mice, though after the onset of pathology, all amyloid models of AD examined have increased TREM2 RNA and protein levels." (PMID 28768545, 2017). "This notion should be considered when interpreting AD research assessing microglial dysfunction, such as studies examining the effect of TREM2 disruption in animal models of amyloidosis." (PMID 29311768, 2017). "We next used the ex vivo assay to investigate TREM2‐dependent antibody‐stimulated amyloid plaque clearance." (PMID 27402340, 2016). "TREM2 expression in microglia is associated with phagocytic clearance of extracellular debris, such as apoptotic neurons, raising the possibility that TREM2 could regulate microglial mediated clearance of extracellular Aβ, and ultimately amyloid plaque deposition." (PMID 24893973, 2014). "Moreover, translocator protein (TSPO)-PET and FDG-PET imaging have demonstrated that TREM2 activation enhances microglial activity and glucose metabolism in amyloid mouse models." (PMID 40247363, 2025). "In cell models with the TREM2 Arg62His variant, the microglia failed to be localized properly around the amyloid plaques, leading to increased expression of TMEM119." (PMID 40806186, 2025). "Since TREM2 facilitates microglial phagocytosis of amyloid plaques, reduced TREM2 activity due to the R47H substitution may result in brain damage through impaired clearance of these toxic products." (PMID 40940798, 2025). "Particularly, since amyloid-induced neurotoxicity can depend on CD36/TLR4/TLR6-mediated inflammatory pathways, chronic inflammation induced by TREM2 mutations can directly increase neurotoxicity, which may accelerate AD-related neurodegeneration." (PMID 40806186, 2025).